MMP1 (matrix metallopeptidase 1)
Diseases named in the same sentence as MMP1 in open-access papers (continued):
Sharing a sentence is not in itself a finding about the gene and the disease.
tumor (continued). "If we assume, as for MMP1, that the higher plasma MMP8 levels reflect a lower expression in the tumour tissue; then the positive relation of plasma MMP8 with premenopausal status, and as such earlier onset, supports the notion of a protective role of MMP8 in cancer." (PMID 18366705, 2008). "Fibroblast invasion-promoting capacity (IPC) was analyzed in relation to donor type (tumor or non-tumor patient), MMP-1, MMP-3, and MMP-9 SNP genotype and MMP activity using independent samples t test and analysis of variance." (PMID 17922906, 2007). "Three distinct patterns of MMP-1 expression (high, medium, and low) were apparent in the tumour epithelium (n=363), whereas two patterns of MMP-1 expression (positive and negative) were displayed by the stromal component (n=402)." (PMID 17311017, 2007). "This showed that the MDA MB 468 tumor cells used in the invasion assays in this study do not express MMP-1 or MMP-3, even following culture with fibroblast CM, whereas the fibroblast populations express both of these MMPs." (PMID 17922906, 2007). "MMP-1 promoter genotypes of OSCC cases were stratified by clinical parameters including gender, age, T category, lymph-node metastasis (N category), tumor location in the oral cavity, status of alcohol intake and smoking." (PMID 17919326, 2007). "Both MMP-1 and MMP-3 have been shown to affect the motility and invasion of tumor cells directly." (PMID 17922906, 2007). "In the Hs578T xenograft stroma, MMP-1 was absent while MMP-3 was observed at a higher level in the stroma as compared to the tumour cells." (PMID 16430785, 2006). "They showed a correlation for MMP1 expression and tumour aggressiveness, but no detectable expression for MMP3." (PMID 16901349, 2006). "Besides overexpression of MMP7, a known β-catenin-dependent target gene in colon cancer, the results show an overexpression of MMP1, MMP3, MMP11, MMP12 and MMP13 in desmoid tumours compared to normal fibroblasts (fascia tissue)." (PMID 15054469, 2004). "The identification of MMP1 and PIM1as potential targets reinforces the hypothesis that EGCG may modulatecell adhesion and invasion through direct or indirect effects on thesepathways, supporting its multifaceted action on the tumor microenvironment." (PMID 40821580, 2025). "While in vitro studies provide valuable insights, they may not fully account for the interactions between tumor cells and the surrounding stromal or immune cells, which could influence MMP1 expression and its role in drug resistance." (PMID 40287412, 2025). "In addition, a soluble form of CD200 (sCD200), released following CD200 ectodomain shedding by matrix metalloproteinase-1 (MMP1) and ADAM19 metallopeptidase, is able to engage CD200R1, can be quantified in the serum, and has been correlated with worse tumor prognosis in CLL and GBM patients." (PMID 40904466, 2025). "For the first time, we demonstrated that SPANXB1 can upregulate MMP1 by modulating YY1 and histone H3R17me2 modifications, thus providing a novel insight into the role of SPANXB1 as a chromatin-binding protein and its potential as a therapeutic target for managing tumor metastasis." (PMID 40885703, 2025). "Overall, 100% of tumor cells exhibited cytoplasmic MMP1 expression irrespective of their origin." (PMID 38891088, 2024). "There were no changes between IDC stratified by tumor size high MMP ratios were also associated with shorter relapse-free survival in patients with DCIS (p-value < 0.001) considering both 3’MMPs/5’MMPs and MMP1/MMP8 ratios." (PMID 38017545, 2023). "Endothelial PAR1 is a non-tumor cell/non-matrix target of MMP1 produced by carcinoma cells." (PMID 37667257, 2023). "Moreover, treatment with MMP1 short hairpin RNA reduced the expression of ECM molecules such as N-cadherin and vimentin and the expression of p-Akt and c-Myc, which are involved in tumour and metastasis formation." (PMID 35954423, 2022).
tumor (continued). "On the other hand, MMP1-mediated tumor progression could be regulated negatively by circDLC158, CIC59 and MTAP60 and positively by 14–3-3σ61, MPP362 and c-Jun63, indicating multiple pathological pathways of MMP1 carcinogenesis in HCC." (PMID 35948625, 2022). "In contrast, most of the tumor cells had no HER2/neu expression, low VEGF and MMP1 expression (weak expression in less than 25% of tumor cells), and high E-cadherin expression (strong expression in more than 50% of tumor cells), which indicated a favourable course of the carcinoma." (PMID 34636027, 2022). "However, it is difficult to explain the negative correlation between MMP1 and Th17 (induce immune response to bacteria and fungi), Tgd (adjuvant tumor killing), EC, CMP and HSC, as well as the positive correlation with CLP." (PMID 35948625, 2022). "Furthermore, ADAMTS-1 and MMP-1 act in concert to not only enhance invasion through the ECM and endothelium but also to promote tumor colonization in the bone microenvironment through an intricate pro-osteolytic signaling cascade that involves tumor cells, osteoblasts, and osteoclasts." (PMID 36338393, 2022). "By contrast, in RasV12; scrib−/− eye disc tumor-bearing larva, the TAHs also secrete Eiger and contribute to JNK signaling through MMP1 expression within the tumor arguing for a tumor-invasion supportive role although no observation on tumor growth has been made." (PMID 34445578, 2021). "In addition to enhanced rates of cancer cell intravasation and dissemination, RT-induced MMP-activation (MMP-1/-2/-3/-9/-14) and subsequent degradation of the TME and the mucosal tissue adjacent to the irradiated tumor site, can induce strong normal tissue toxicities." (PMID 34055644, 2021). "Indeed, in our study, we found that migratory and invasive abilities were increased in tumour spheres, compared to parental A549 cells; expression levels of N‐cadherin, vimentin, MMP‐9 and MMP‐1 were also increased in tumour spheres, compared to parental A549 cells." (PMID 32396269, 2020). "Thus, our data suggest that when high ROS is induced in Hipk tumor-like cells as a result of inhibition of mitochondrial energetics, the high ROS can potentiate JNK activation and downstream MMP1 induction, which probably triggers tumor invasion and exacerbates tumor progression." (PMID 33199523, 2020). "Matrix Metallopeptidase 1 (MMP1) mRNA in extracellular vesicles (EVs) secreted by OC cells can induce apoptosis of peritoneal mesothelial cells, thereby destroying the peritoneal mesothelial barrier and promoting the transfer of tumor cells to the peritoneum in OC patients." (PMID 32208363, 2020). "TCONS_00012883 could promote the tumor growth and aggressiveness of cancer cells and activate the PI3K/AKT pathway through cooperating with DDX3 to facilitate the transactivation of YY1 and transcriptional alteration of MMP1." (PMID 33135346, 2020). "MMPs as a family of zinc-dependent proteolytic enzymes include MMP-1, MMP-3, and MMP-9, have the ability to degrade collagen and other ECM proteins, and play a crucial role in different pathophysiology conditions, such as invasion, vascular remodeling, angiogenesis, and tumor metastasis." (PMID 31762729, 2019). "Moreover, it has been well established that a transcription factor, nuclear factor κB (NF-κB), is activated in skin keratinocytes by UV irradiation and leads to the augmentation of the levels of MMP-1, thus suppression of NF-κB pathway would freeze the UVB-induced skin photoaging process." (PMID 31207929, 2019). "NOB reduces the tumor-invasive activity of human fibrosarcoma HT-1080 cells through suppressing the expressions of matrix metalloproteinase-1 (MMP-1) and MMP-9, and exerts inhibitory effects on the production of MMP-1, -3 and -9 in rabbit synovial fibroblasts in vitro." (PMID 31398899, 2019).
tumor (continued). "The role of MMP-1 in highly metastatic human epidermoid carcinoma, HEp3, was shown to be PAR1-dependent and shown to be an important regulator of vascular permeability, tumor cell intravasation, and metastatic dissemination in agreement with our data in vascular integrity." (PMID 30065181, 2018). "However, the expression of MMP-1, MMP-2, and MMP-9 was not different between primary NSCLC tumor and metastatic lymph node (MMP-1 and MMP-9 not shown)." (PMID 28915603, 2017). "Thus, MMP-1 and MMP-3 transcripts were apparently decreased after treatment with sorafenib, providing a possible explanation for its potent roles on controlling KF migration as well as tumor cell invasion and metastasis." (PMID 27339758, 2016). "Therefore in the future, simultaneous inhibition of integrin αvβ3 with MMP1 and LAMA5 may provide greater efficacy, and an alternate approach to destabilize tumour vasculature." (PMID 27324842, 2016). "However, the rate of cells stained with MMP-1 was not statistically different between the primary tumor and the metastatic lymph nodes (P = 0.07)." (PMID 25945089, 2015). "Neoplastic tumours are characterised by their absence of differentiation, disrupted apico-basal polarity and their upregulation of Matrix metalloprotease 1 (Mmp1), a target of JNK signalling involved in extracellular matrix remodelling, which is a marker for tumour metastasis." (PMID 24104056, 2014). "Finally, we have identified tumor-derived PDGF-BB and MMP-1 as novel prognostic markers." (PMID 25483099, 2014). "Moreover, we found that RANKL could promote the expression of MMP1, MMP3 and MMP9, which indicated that increased expression of MMPs was involved in the process that RANKL promoted tumor invasion and migration via NF-κB pathway." (PMID 25268581, 2014). "The elevated tissue MMP-1 activity in carriers of 2G/2G genotype could be responsible for the degradation of fibrillar collagens and other components of ECM, thus facilitating the progress of the neoplastic disease." (PMID 23108733, 2013). "However, we found a negative, but not a significant correlation between tumour cell MMP-1 expression and ER expression." (PMID 21835023, 2011). "In fact, the tumor microenvironment alterations in human cancer not only influence tumor progression and predict prognosis, but also have major effects on the efficacy of cancer therapy, especially the targeted therapy aimed at growth factor receptors and secreted proteins, such as HER-2 and MMP-1." (PMID 21834986, 2011). "Study using breast cancer samples demonstrates that the expressions of MMP-1, MMP-2, MMP-3, MMP-9, urokinase-type PA, and tissue-type PA, and inhibitors (TIMP-1 and TIMP-2) were stronger or equivalent in tumor cells than in fibroblasts or inflammatory cells within the tumor section." (PMID 21152266, 2010). "Hence MMP1 was present only in human tumor cells without an induced contribution from the surrounding murine cells." (PMID 21170377, 2010). "In addition, our data showed that the expression of MMP-1, 7, 9, 11, 13, 14, TIMP-1, and 2, as a function of the cellular type (tumour cell, fibroblast, and/or inflammatory mononuclear cell) expressing the protein, was significantly associated with a shorter relapse-free survival." (PMID 17342087, 2007). "Notably, regardless of SG treatment, MMP1 knockdown further enhanced tumor growth inhibition." (PMID 40287412, 2025). "Therefore, tumor cells destroy the normal connection of vascular endothelium by secreting protein angiopoietin-like 4 (Angptl4) and various cytokines, such as cyclooxygenase-2 (COX-2), epiregulin (EREG), and MMP-1/2, thereby promoting the extravasation of tumor cells." (PMID 40356596, 2025). "RT-PCR analysis revealed that among these candidates, MMP-1 exhibited the most significant differential expression, identifying it as a target for further investigation to clarify the specific signaling pathway through which AGBL4 may promote GBM tumor progression." (PMID 39007144, 2024).
tumor (continued). "Moreover, absence of MMP1 decreased tumor migration but not growth in vivo." (PMID 36105241, 2022). "In immune analysis, ICAM1, IL1B, IL-6, MMP1, MMP3, MMP9, and SERPINE1 all showed positive correlations with most immune cells, implying that CC and MF may exert an antitumor activity by interacting with these genes and immune cells, and thus control tumor development." (PMID 35783510, 2022). "SCCF2 and SCCF3 showed expression of MMP-1/-2/-9 at gene and protein level, suggesting that they might contribute to invasive potential of FOSCC cells, in agreement with studies on hOSCC that demonstrate that these MMPs play a relevant role in determining the invasive phenotype of tumor cells." (PMID 32292795, 2020). "The lack of MMP-1 expression in peritoneum already invaded by tumour could possibly be explained by mechanisms that keep tissues in a remodelling state in the invasion zone between normal peritoneum and tumour." (PMID 29623449, 2018). "In addition, vascular remodeling factors, including epiregulin, cyclooxygenase 2 (COX2), MMP1, and MMP2, can promote breast cancer lung metastasis through facilitating the release of tumor cells into the circulation system and breaching lung capillaries by circulating tumor cells." (PMID 28356139, 2017). "A previous study revealed four important cancer invasion-related genes, MMP-1, MMP-2, EGFR and COX-2, in a variety of human cancers, including GC, which may manipulate the migration of tumour cells and the formation of new tumours by facilitating the release of tumour cells into the circulation." (PMID 23833643, 2013). "Thus, although ab overexpression may contribute to the invasive properties of the tumours by promoting the expression of targets such as Mmp1, it is not sufficient to promote tumour invasion in the absence of JNK signalling." (PMID 23874226, 2013). "In particular, MMP-2 acts mainly as virulence gene that may allow tumours to aggressively invade, colonize and grow in the lungs without markedly contributing to primary tumour growth, whereas MMP-1, determine metastatic potential of breast cancer to produce lung metastases." (PMID 23905066, 2012). "Although MMP‐1, MMP‐8, and MMP‐13 exhibit the ability to degrade native fibrillar type I and type III collagen, recent studies have revealed that in UV‐mediated skin collagen damage, there is no significant disparity between the roles of MMP‐8 and MMP‐1." (PMID 39230065, 2024). "ALDH1A3 also upregulated MMP1 and MMP8; however, these were not highly co‐expressed with ALDH1A3 in the patient tumour data." (PMID 37753740, 2024). "Intriguingly, these observations were almost further validated by our real‐time qPCR results of five pairs of tumor and adjacent nontumor samples, such as COL1A1, MMP1, MMP10, CXCL8, and IL1B." (PMID 34821009, 2022). "On the other hand, there were insufficient amounts of pro-metastatic proteins (VEGF and MMP1); an absence of HER2/neu expression; and the severe adhesive capacity of tumor cells prevented local and remote tumor spread." (PMID 34636027, 2022). "The protein expression of MMP1, CD24, SDC1, and SPP1 was significantly correlated with tumor grade and subtype but not with tumor stage." (PMID 35037689, 2022). "Unlike common anticancer agents, BB94 is a potent extracellular inhibitor of MMP-1, MMP-2, MMP-3, MMP-7, and MMP-9, and thus, it should be released in the extracellular space rather than in tumor cells." (PMID 35440570, 2022). "Simultaneously, the majority of the tumor cells were either negative or had low (weak expression in less than 25% of tumor cells) VEGF and MMP1 cytoplasmic expression." (PMID 34636027, 2022). "MMP1 and MMP9 were not upregulated in tumor cells co-cultured with CAFs in 2D, but these MMPs were upregulated in tumor tissue from HNSCC patients compared to normal oral tissue." (PMID 34283070, 2021).
tumor (continued). "MMP1 and MMP11 do not appear to be upregulated in PBMC; however, our previous results demonstrate that MMPs are highly expressed by tumor infiltrated cells and also by surrounding sentinel lymph nodes cells in aggressive BC." (PMID 33396463, 2020). "Specifically, MMP1 staining was more intense in the tumor section of NSCLC with IPF compared with the paired IPF section, and compared with the tumor section of NSCLC without IPF." (PMID 33046043, 2020). "Here, several tumor EMT markers (Twist1, Snail, MMP1, and MMP9) were evaluated, but metformin did not inhibit EMT in MCF7/ADR." (PMID 29416762, 2018). "Several angiogenesis-related genes like MMP1, MMP3, SFRP2, CXCL8, SERPINE1 and TNFAIP6 were up-regulated in tumors with necrosis, as identified among genes differentially expressed between tumor samples with and without necrosis." (PMID 26485755, 2015). "There have been reports linking other extracellular proteases, such as MMP-9, MMP-1 and uPA with FAK signalling in other tumour cell types, but until now MMP-2 has not been reported to be involved." (PMID 18349846, 2008). "Plasma concentrations of MMP1, MMP3, MMP9, TIMP2, and the MTC1 did not correlate to tumour stage, grade, lymph node involvement, or distant metastasis." (PMID 16901349, 2006). "In the MDA-MB-231 spleen metastasis, the tumour cell showed high MT1-MMP (3+), and low MMP-3 expression (1+), but no detectable MMP-1 gene expression (0+)." (PMID 16430785, 2006). "Plasma concentrations of MMP1, MMP3, MMP9, TIMP2, and MTC1 did not correlate to tumour stage and grade, but also to lymph node involvement or distant metastasis (data not indicated)." (PMID 16901349, 2006). "The expression of MMP-3 correlated to that of MMP-1 (P = 0.03) localized at the tumour mass and stroma of the invasive area, while MMP-2 mRNA was detected widely throughout the stroma independent of MMP-1 expression." (PMID 10362121, 1999). "Thus, the ratio between MMP1 and MMP8 is decreased after IE8 disruption, resembling the profile observed in healthy breast samples as opposed to tumor samples." (PMID 38017545, 2023). "Similarly, gene expression of EPHA2, KDR, LAMC2, MMP1, and MMP14 did not vary between tumours of mice treated without and with aspirin." (PMID 32246008, 2020). "Further, levels of related MMPs including MMP1, MMP8, MMP14, MMP2 and MMP9 which have previously been shown to affect tumor cell invasion were not evaluated in these studies and could compensate for MMP13 levels." (PMID 25880591, 2015). "Separate analyzes of MMP1, MMP2, MMP3, MMP9, TIMP1, TIMP2, and MTC1 in plasma do not allow a prognostic prediction for tumour grading, staging, or metastasis, but certain combinations could be very helpful." (PMID 16901349, 2006). "Curiously, it was observed that MMP1 gene expression was higher when PBMC (both C-PBMC and BC-PBMC) were co-cultured with CAF rather than with NF, although differences between co-culture with NF or CAF were not statistically significant, probably due to tumor heterogeneity." (PMID 33396463, 2020).